YY1 (YY1 transcription factor)
Diseases named in the same sentence as YY1 in open-access papers (continued):
Sharing a sentence is not in itself a finding about the gene and the disease.
autoimmune hypothyroidism (1 paper, 2025). "This case report describes a pediatric patient with a de novo heterozygous YY1 mutation (c.385del, p.D129Ifs*127), presenting with autoimmune hypothyroidism (Hashimoto’s thyroiditis, HT), nanophthalmos, and multisystem developmental anomalies." (PMID 40655401, 2025).
autoimmune thyroid disease (1 paper, 2025). Inflammatory disease of the thyroid gland due to autoimmune responses leading to lymphocytic infiltration of the gland. "This case suggests that YY1 mutations may promote autoimmune thyroiditis through: disrupting immune tolerance mechanisms and amplification of autoreactive immune responses." (PMID 40655401, 2025). "As a single case, coincidental comorbidity cannot be excluded; however, the patient’s family history of autoimmune thyroid disease suggests a possible inherited predisposition independent of YY1 mutation." (PMID 40655401, 2025).
bile duct cancer (1 paper, 2021). "Flow cytometry was used to detect the effects of silencing and overexpressing YY1 and EMI2 on apoptosis in the bile duct cancer cells, and the results showed that YY1 activated EMI2, thus, inhibiting apoptosis." (PMID 34933678, 2021). "Subsequently, in vivo and in vitro experiments were conducted to verify the effects of silencing and overexpressing EMI2 and YY1 on the proliferation, invasion, and metastasis of the bile duct cancer cells." (PMID 34933678, 2021). "YY1 is involved in regulating the progression of bile duct carcinoma." (PMID 34933678, 2021). "TCGA data showed that YY1 was highly expressed in bile duct carcinoma." (PMID 34933678, 2021). "YY1 activates EMI2 and promotes PI3K/AKT/P27 signaling, thus, increasing the proliferation and metastasis and inhibiting the apoptosis in bile duct carcinoma." (PMID 34933678, 2021). "This suggested that YY1 may activate EMI2 to promote cell cycle progression and inhibit apoptosis in bile duct cancer cells." (PMID 34933678, 2021). "Secondly, we did not verify the effect of YY1 on the proliferation and metastasis of bile duct carcinoma in vivo." (PMID 34933678, 2021). "Therefore, we speculated that YY1 transcriptionally activated the expression of EMI2 and promoted the progression of bile duct carcinoma through the PI3K/Akt signaling pathway." (PMID 34933678, 2021).
cervical squamous cell carcinoma (1 paper, 2018). A squamous cell carcinoma arising from the cervical epithelium. "In summary, the present study demonstrated that the abnormal expression of YY1, E-cadherin and HPV16 E6 were associated with cervical squamous cell carcinoma progression." (PMID 29470526, 2018). "The expression of YY1 in patients with cervical squamous cell carcinoma subgrouped by clinical pathologic factors." (PMID 29470526, 2018).
co-infection (1 paper, 2025). "Moreover, it can be seen that in the context of co-infection, the protein levels of YY1 were increased when ORF3a was knocked down." (PMID 40668819, 2025).
delirium (1 paper, 2023). A disorder characterized by confusion; inattentiveness; disorientation; illusions; hallucinations; agitation; and in some instances autonomic nervous system overactivity. "The YY1 regulates a significant number of genes associated with the nervous system, hence it might have greater involvement with delirium pathophysiology." (PMID 37993790, 2023).
diabetic retinopathy (1 paper, 2021). "Moreover, we found the dysregulated miR-195, YY1, VEGFA, and Snail1 were associated with diabetic retinopathy development." (PMID 34267179, 2021). "Similarly, here we also found YY1 could upregulate VEGFA and Snail1 expression to regulate diabetic retinopathy development." (PMID 34267179, 2021).
embryonic carcinoma (1 paper, 2012). "For instance, complete ablation or knock-down of YY1 leads to growth inhibition in embryonic fibroblasts, HeLa cells, DT40 cells, and embryonic carcinoma cells." (PMID 22292011, 2012).
emphysema (1 paper, 2019). "YY1 and ZEB1 also appeared as the regulators of the CCP formed between LC and Emphysema, giving another layer of evidence of their importance in the establishment of LC in patients with an emphysema antecedent." (PMID 31867044, 2019).
endometrioid endometrial carcinoma (1 paper, 2022). "The expression of YY1 was increased in endometrioid endometrial carcinoma (EESCA)." (PMID 35359580, 2022).
fibroid (1 paper, 2019). "Our previous work has determined the regulation of transcription factor YY1 in pathogenesis of fibroid lung." (PMID 31703732, 2019).
hyperopia (1 paper, 2025). A refractive error in which rays of light entering the eye parallel to the optic axis are brought to a focus behind the retina, as a result of the eyeball being too short from front to back. "In the present case, we identified a mutation in the YY1 gene, which is associated with nanophthalmos and may underlie the ocular abnormalities such as strabismus and hyperopia." (PMID 40655401, 2025).
Hypertension (1 paper, 2025). The presence of chronic increased pressure in the systemic arterial system. "Taken together, these results highlight the critical role of the YY1/Mettl3 axis in mitigating hypertension and regulating blood pressure under both normal and hypertensive conditions." (PMID 40795179, 2025). "Moreover, our results highlight the clinically relevant role of the YY1/Mettl3 axis in mitigating hypertension and regulating blood pressure under both normal and hypertensive conditions." (PMID 40795179, 2025). "Additionally, our results demonstrate a clinically relevant role for the YY1/Mettl3 axis in mitigating hypertension and regulating blood pressure under both normal and hypertensive conditions." (PMID 40795179, 2025).
idiopathic dilated cardiomyopathy (1 paper, 2019). Decreased function of the heart associated with cardiac enlargement and congestive heart failure, of unknown cause. "Importantly, YY1 is shown to be upregulated in human idiopathic dilated cardiomyopathy (IDC) and heart failure." (PMID 31705051, 2019).
immune deficiencies (1 paper, 2025). "These age-related immune deficiencies can be attributed to reduced transcription of YY1, and grasping this connection is fundamental to addressing age-related immune challenges." (PMID 39736852, 2025). "The decline in miR-181a with age and its connection to reduced YY1 transcription offer valuable insights into the mechanisms underpinning age-related immune deficiencies." (PMID 39736852, 2025).
inflammatory bowel disease (1 paper, 2016). A spectrum of small and large bowel inflammatory diseases of unknown etiology. "Next, the role of YY1 in Treg cell function in vivo was examined using an animal model of inflammatory bowel disease." (PMID 26892542, 2016).
intracranial aneurysms (1 paper, 2022). "Analysis of transcription factors revealed that YY1 may be associated with the development of intracranial aneurysms." (PMID 35860808, 2022).
invasive breast carcinoma (1 paper, 2014). A carcinoma that infiltrates the breast parenchyma. "YY1 induces expression of cyclooxygenase-2 (COX-2), which is overexpressed in 40% of human invasive breast cancers and mediates bone metastasis." (PMID 24674326, 2014).
keloid (1 paper, 2024). An irregularly shaped, elevated mark on the skin caused by deposits of excessive amounts of collagen during wound healing. "Furthermore, we found that 2 TFs, NR3C2 and YY1, are less expressed in keloid and AD samples than in the control group of GSE158395 and GSE12121." (PMID 38476235, 2024). "Finally, two TFs of CCR5, NR3C2 and YY1, were identified, both of which were downregulated in keloid and AD tissues." (PMID 38476235, 2024).
kidney angiomyolipoma (1 paper, 2013). An angiomyolipoma arising from the kidney. "Collectively, the data indicate the major role of YY1 in the regulation of αSMA and fibrosis of kidney angiomyolipomas of TSC patients." (PMID 23705901, 2013). "Furthermore, tumor tissue showed higher protein expression of YY1 compared to control kidney tissue suggesting that YY1 plays a major role in the regulation of fibrosis in kidney angiomyolipoma tissue." (PMID 23705901, 2013). "In addition, binding of YY1 to α-SMA promoter may provide a mechanism for enhancing the expression α-SMA to increase cell fibrosis in kidney angiomyolipoma of TSC patients." (PMID 23705901, 2013). "Because YY1 can directly bind to the promoter regions of α-SMA gene and is required for its expression, we suggest that YY1 directly regulates a-SMA that is involved in fibroblast activation and myofibroblast differentiation in kidney angiomyolipomas." (PMID 23705901, 2013).
lentivirus infection (1 paper, 2024). Virus diseases caused by the Lentivirus genus. "To investigate the biological function of USP7-mediated YY1 stabilization in CRC, we established stable cell lines with knockdown of YY1, USP7, or both using lentivirus infection." (PMID 38769122, 2024).
lymphoid leukemia (1 paper, 2023). A malignant lymphocytic neoplasm of B-cell or T-cell lineage involving primarily the bone marrow and the peripheral blood. "The role of the YY1 protein in carcinogenesis and the progression of solid tumors is well established, as well as in lymphoid leukemia." (PMID 37568827, 2023).
major depressive disorder (1 paper, 2024). An episode of depression lasting two or more weeks without an intervening episode of mania. "Data from clinical studies indicate that plasma levels of YY1 are significantly elevated in patients with major depressive disorder." (PMID 38612681, 2024).
malignant peritoneal mesothelioma (1 paper, 2025). An aggressive malignant mesothelioma that arises from the peritoneum. "Recently, pediatric malignant peritoneal mesothelioma cases have been genetically studied, with alterations observed in ALK, EWSR1, FUS1, YY1, or in AURKA, AURKC, HLA-1B, ZNF-217, OR5F1, and MEN1 genes, but not in BAP1." (PMID 40725095, 2025).
mantle cell lymphoma (1 paper, 2018). Mantle cell lymphoma is a rare form of malignant non-Hodgkin lymphoma affecting B lymphocytes in the lymph nodes in a region called the ``mantle zone''. "YY1 expression was evaluated at mRNA and protein level in a panel of 13 human B-NHL cell lines representing different subtypes (BL, DLBCL, FL and mantle cell lymphoma, MCL) and a normal B lymphoblastoid cell line (NC-NC)." (PMID 29564133, 2018).
microcephaly (1 paper, 2019). A congenital or acquired developmental disorder in which the circumference of the head is smaller than normal for the person's age and sex. "Loss of Yy1 before the onset of neurogenesis resulted in microcephaly owing to the depletion of NPCs." (PMID 31097699, 2019). "Conditional ablation of Yy1 at early stages of cortical development resulted in microcephaly owing to decreased cell proliferation and increased cell death." (PMID 31097699, 2019).
migraine (1 paper, 2018). "Yy1 was enriched among inflammatory pathway genes dysregulated in a transgenic mouse model of migraine." (PMID 30618656, 2018).
mood disorder (1 paper, 2022). A cognitive disorder a disturbance in which the person's mood is hypothesized to be the main underlying feature. "Given the increased prevalence of stress-related mood disorders in women, an examination of neuronal YY1 function and stress adaptation in female subjects is especially important." (PMID 35013139, 2022).
nanophthalmos (1 paper, 2025). "This novel association between YY1 mutations and nanophthalmos suggests YY1 may represent a candidate gene for the etiology of this rare ocular phenotype." (PMID 40655401, 2025).
nephritis (1 paper, 2024). Inflammation of renal tissue. "Further investigation is needed to elucidate the interactions between oxymatrine, YY1, and nephritis, potentially uncovering novel therapeutic pathways for treating this condition." (PMID 39596325, 2024).
oral squamous cell carcinoma (1 paper, 2022). "Ying Yang1 (YY1) has already been discussed in oral squamous cell carcinoma (OSCC), but the knowledge about its mediation on long non-coding RNA KCNQ1 overlapping transcript 1/microRNA-506-3p/synaptophysin like 1 (Kcnq1ot/miR-506-3p/SYPL1) axis in OSCC is still in its infancy." (PMID 35778739, 2022).
Pancytopenia (1 paper, 2025). An abnormal reduction in numbers of all blood cell types (red blood cells, white blood cells, and platelets). "Our results showed that YY1 deletion in fetal hematopoiesis leads to pancytopenia and neonatal death." (PMID 40762953, 2025).
pediatric osteosarcoma (1 paper, 2023). An osteosarcoma occurring in childhood. "On the other hand, the expression of YY1 was decreased in PDAC, NPC, pediatric osteosarcoma, etc., and negatively correlated with its clinical progression and a poor prognosis, suggesting that the low YY1 expression predict poor prognosis of these tumors." (PMID 37081988, 2023).
rectal tumors (1 paper, 2019). "CYT-high rectal tumors on the other hand, had recurrent deletions at loci 3p21.31 (RHOA), 5q22.2 (APC), 10q26.2 (MGMT), 14q32.2 (AKT1, EIF5, YY1), 18q21.2 (SMAD4, MAPK4), and a single amplification in 7p15.3 (STK31)." (PMID 31429779, 2019).
Rett syndrome (1 paper, 2023). A severe neurodevelopmental disorder affecting the central nervous system.
Skeletal muscle atrophy (1 paper, 2024). The presence of skeletal muscular atrophy (which is also known as amyotrophy). "However, only high-dose AM was able to improve gastrocnemius muscle atrophy in the model mice, with Coll, MSTN, and YY1 being phenotypes of skeletal muscle atrophy; FBXO32 and TRIM63 were indicators of protein synthesis." (PMID 39239655, 2024).
soft tissue sarcoma (1 paper, 2011). A malignant neoplasm arising from muscle tissue, adipose tissue, blood vessels, fibrous tissue, or other supportive tissues excluding the bones. "We have recently demonstrated that YY1 is involved in CXCR4 and VEGF pathways which have both been genetically amplified and correlated with poor survival of soft-tissue sarcomas." (PMID 22047406, 2011).
squamous intraepithelial lesions (1 paper, 2022). "Interestingly, a similar dislocation of YY1 was previously reported in high-grade squamous intraepithelial lesions, which further underscores the importance of YY1 as a crucial transcriptional regulator targeted by HPV." (PMID 35406439, 2022).
status epilepticus (1 paper, 2015). Status epilepticus is defined as a continuous seizure lasting more than 30 min, or two or more seizures without full recovery of consciousness between any of them. "Here, we explored the transcriptional response of genes associated with polycomb repressive complex (PRC) 1 (Ring1A, Ring1B, and Bmi1) and PRC2 (Ezh1, Ezh2, and Suz12), as well as additional transcriptional regulators Sirt1, Yy1, and Yy2, in a mouse model of status epilepticus (SE)." (PMID 25806020, 2015).
Stroke (1 paper, 2018). Sudden impairment of blood flow to a part of the brain due to occlusion or rupture of an artery to the brain. "CP2, E47, IK3, TAL1, USF, and YY1 are TF that has not been previously shown to be associated with stroke." (PMID 29856744, 2018).
tongue squamous cell carcinoma (1 paper, 2022). A squamous cell carcinoma that arises from the tongue. "Also, a liaison has been observed between overexpressed YY1 and inferior survival of tongue squamous cell carcinoma (TSCC) patients, indicating that YY1 may regulate the malignant phenotype of SCC." (PMID 35778739, 2022).
tumor suppressor (1 paper, 2024).
Waardenburg syndrome (1 paper, 2012). A disorder characterized by varying degrees of deafness and minor defects in structures arising from neural crest, including pigmentation anomalies of eyes, hair, and skin. "Here, we generated Yy1 conditional knockout mice in the melanocyte-lineage and observed profound melanocyte deficiency and premature gray hair, similar to the loss of melanocytes in human piebaldism and Waardenburg syndrome." (PMID 22570637, 2012). "Although the Waardenburg syndrome genes PAX3, SOX10, MITF, EDN3 and EDNRB were not dramatically affected at the mRNA level, expression of the piebaldism gene KIT was significantly down-regulated upon loss of YY1." (PMID 22570637, 2012).
Wilms tumor (1 paper, 2008). An embryonal neoplasm characterized by the presence of epithelial, mesenchymal, and blastema components. "Important for their relation to Wilm's Tumor, several of these TFs have previously been implicated in cancer (NANOG, GLI1, E2F1, POU5F1/OCT4, SPI-1, YY-1, GATA1, and C/EBP-β)." (PMID 18564415, 2008).